IL1B (interleukin 1 beta)
Diseases named in the same sentence as IL1B in open-access papers (continued):
Sharing a sentence is not in itself a finding about the gene and the disease.
Insulin resistance (continued). "These recruited M1 macrophages secrete pro-inflammatory cytokines, including TNF, IL-6, and IL-1β, and oxidative metabolites such as superoxide and nitric oxide (NO), resulting in inflammation and insulin resistance." (PMID 36838843, 2023). "This, in turn, leads to IL-1β and IL-18 secretion and subsequent insulin resistance through serine phosphorylation of IRS-1 and impairment of insulin signaling." (PMID 37372020, 2023). "Previous studies showed that interleukin (IL)-1β in human blood is positively correlated with insulin resistance." (PMID 36983072, 2023). "It has been also shown that obese individuals experience an increase in pro-inflammatory IL-1α and IL-1β, which consequently lead to insulin resistance." (PMID 37180128, 2023). "On its hand, IL-1β further promotes insulin resistance, triggering TNF-α production and decreasing the phosphorylation of IRS-1, also contributing to β-cell failure and diabetes progression." (PMID 37299482, 2023). "The interventions increased the RER values, which implied an increase in glucose as a substrate of energy metabolism, likely related to their ability to alleviate insulin resistance by reducing IL-1β and TNF-α levels." (PMID 37693249, 2023). "Excessive lipid accumulation was reported to induce insulin resistance in adipocytes, hepatocytes, and skeletal muscle cells by increasing the levels of various proinflammatory cytokines, including IL-1β, IL-6, TNFα, and MCP1." (PMID 35889886, 2022). "Berberine also inhibited AMPK-dependent autophagy in adipose tissue macrophages, which reduced palmitate-induced inflammasome activation, IL-1β release, insulin resistance." (PMID 36700235, 2022). "Among these pro-inflammatory cytokines and adipokines secreted by adipose tissue, interleukin (IL)-1β plays a critical role in chronic low-grade inflammation in adipose tissue and is in part responsible for the development of insulin resistance." (PMID 36234919, 2022). "Mast cells were positively corelated with components of MetS, such as WC, raised TG and insulin resistance, as well as inflammatory markers such as IL-1β and IL-6, suggestive of an inflammatory role in pathogenesis of MetS." (PMID 36103469, 2022). "Research has shown that W. coagulans can inhibit the HFD-induced expression of inflammatory cytokines IL-1β and IL-6 in the liver to improve systemic inflammation and insulin resistance." (PMID 36235858, 2022). "In agreement, our results demonstrated that HF diet induced-insulin resistance was accompanied by increased IL-1β mRNA expression and mature IL-1β secretion in adipose tissue of WT mice, which was reversed by enrichment of endogenous n-3 PUFAs in fat-1 mice." (PMID 36234919, 2022). "In accordance with this finding, high extracellular ATP levels, released through PANX1 channels, lead to the enhancement of the inflammatory state of IL-1β and to insulin resistance in the skeletal muscle fibers of obese mice." (PMID 36552772, 2022). "Studies suggest that dietary MUFAs can reduce IL-1β-mediated adipose dysfunction and insulin resistance via preservation of AMP-activated protein kinase (AMPK) activity which, in turn, quenches NLRP3 inflammasome activation." (PMID 35276849, 2022). "IL-1β activates p38 mitogen-activated protein kinases (p38MAPK), resulting in insulin resistance and disrupts insulin-dependent keratinocyte differentiation and induces keratinocyte proliferation." (PMID 35743091, 2022). "Second, prolonged high levels of IL‐1β are known to also participate in insulin resistance by promoting pancreatic β‐cell dysfunction and cell death." (PMID 35971650, 2022). "Many other inflammatory cytokines and mediators such as IL-1β, IL-6, monocyte chemotactic protein 1 (MCP-1), and macrophage inhibitory factor (MIF) have been implicated in the pathogenesis of insulin resistance." (PMID 35563728, 2022).
Insulin resistance (continued). "Macrophages appear to be the principal source of pro-inflammatory cytokines such as IL-1β and TNFα that can confer insulin resistance in insulin-sensitive cells." (PMID 35955975, 2022). "The IL-1β pathway has also been suggested to drive systemic and tissue inflammation in T2D, thus contributing to peripheral insulin resistance and T2D-related cardiovascular complications." (PMID 35629988, 2022). "And the secretion of IL-1β and IL-18, caused by activation of the NLRP3 inflammasome, is emerging as a powerful determinant of metabolic inflammation and insulin resistance in T2DM patients." (PMID 35355717, 2022). "Interleukin (IL)-1β is implicated in insulin resistance, yet how n-3 PUFAs modulate IL-1β secretion and attenuate HF diet-induced insulin resistance remains elusive." (PMID 36234919, 2022). "Their activation is dependent on the same IKK-β implicated in the pathophysiology of insulin resistance, and results in PPAR-γ mediated secretion of IL-1β, TNF-α, IL-6, IL-12, and IL-23." (PMID 36615781, 2022). "Activated NLRP3 inflammasome and downstream caspase-1 do not affect the ratio of M1/M2 in adipose tissue but promote the secretion of IL-1β and IL-18, leading to insulin resistance." (PMID 35757707, 2022). "IL-1β can promote inflammatory cytokines release by mediating islet β-cell apoptosis or activating the NF-κB pathway, thereby inducing insulin resistance and type 2 diabetes." (PMID 35923203, 2022). "Using SGBS cells and murine in vitro models, Caspase 1 has been previously identified as a key mediator of IL-1β-driven insulin resistance." (PMID 35986215, 2022). "It has been recently shown in a C57BL/6 male mice model that consuming a high-fat diet, enriched with SFAs, induces especially adipose IL-1β inflammation and insulin resistance." (PMID 35276849, 2022). "But in an obese state, Ly6chigh monocytes infiltrate tissues and differentiate into M1 type macrophages, which produce inflammatory cytokines, such as TNF-α, IL-6, IL-1β, and IL-18, and drive insulin resistance." (PMID 36015301, 2022). "In T2DM, as well as in insulin resistance, there is increased production of IL-6, IL-1β, IL-18, tumor necrosis factor (TNF-a), alpha-1 antichymotrypsin and C-reactive protein." (PMID 35453527, 2022). "In the same study, it was demonstrated in vitro that the latter diet can reduce adipose IL-1β secretion and insulin resistance." (PMID 33546399, 2021). "Inflammatory cytokines such as tumor necrosis factor-α, interleukin (IL)-1β and IL-6 activate several inflammatory signaling pathways that promote insulin resistance." (PMID 34887771, 2021). "IL-1β promotes insulin resistance by reducing the tyrosine phosphorylation and mRNA expression of insulin receptor substrate-1, and inducing the expression of tumor necrosis factor α." (PMID 34737754, 2021). "Noticeably, TNFα, IL-1β, IL-18, and IL-6 are the most important cytokines involved in the development of insulin resistance." (PMID 34070553, 2021). "Adipocyte hypertrophy generally increase the expression of pro-inflammatory cytokines including tumor-necrosis factor-α (TNF-α), IL-6, and IL-1β in the human patients with insulin resistance." (PMID 34484126, 2021). "IL-1β has been shown to promote β-cell destruction in Type 1 Diabetes and increase insulin resistance." (PMID 33904577, 2021). "IL-1β potentially serves as messenger in inter-organ crosstalk during the development on metabolic disorders, such as insulin resistance." (PMID 33920187, 2021). "In particular, ATM-derived proinflammatory cytokines, such as TNF-α and IL-1β, are similar to classically activated M1-type macrophages that directly contribute to insulin resistance or type 2 diabetes." (PMID 33794740, 2021). "Our previous study confirmed that FoxO6-mediated IL-1β is involved in hepatic inflammation and insulin resistance via TF/PAR2/Akt pathway in aging and diabetic liver." (PMID 34631216, 2021).
Insulin resistance (continued). "M1 macrophages induce an inflammatory and insulin resistance state through the inhibition of insulin signaling, indirectly produced by TNF-α, IL-6, and IL-1β, while M2 macrophages protect against insulin resistance by an IL-10-dependent mechanism." (PMID 34944461, 2021). "IL-1β activated by NLRP3 inflammasome can worse insulin resistance in human adipocytes, moreover, inhibition of IL-1β can reduce hyperglycemia in obese/diabetic rats." (PMID 33796528, 2021). "Evidence indicates that TNF-α and IL-1β facilitate insulin resistance development by elevating blood insulin and HDL cholesterol levels 3 and insulin resistance suppresses keratinocyte differentiation, resulting in persistent proliferation." (PMID 33391503, 2021). "VA treatment also showed decreased expression of two key inflammatory markers, TNFα and IL1β, in the intestine, but research is needed to understand the effect of VA on gut microbiota during insulin resistance and related mechanisms." (PMID 34946118, 2021). "Studies on obese patients have outlined that insulin resistance and related disorders are characterized by a cytokine imbalance, with high levels of TNFα, IL-6, IL-1β, CRP, and NF-κB." (PMID 33995414, 2021). "After activation of the NLRP3 inflammasome, IL-1β is released to promote insulin resistance and induce β-cell functional impairment and apoptosis of the inflammasome." (PMID 33854691, 2021). "Pellino3-deficient mice show heightened diet-induced inflammation and increased IL-1β levels, resulting in exacerbation of insulin resistance." (PMID 33531049, 2021). "It is possible that IL-6 in combination with other inflammatory markers such as IL-1b, TNF-a, IL-18 and IL-17 links insulin resistance to NMOSD risk." (PMID 33879088, 2021). "IL-1β and IL-18 contribute to insulin resistance and islet β-cell damage in T2DM; they are classic pro-inflammatory cytokines of the IL-1 family." (PMID 34737846, 2021). "Attenuation of TNFα/IL-1β/CCL2-mediated inflammation in metabolic organs has been shown to improve insulin resistance, consistent with the observed reduction of fasting insulin and HOMA-IR in KrO-treated mice." (PMID 34444996, 2021). "Kupffer cells and recruited macrophages secrete inflammatory cytokines such as TNF-α, interleukin-1 beta (IL-1β), and IL-6, prompting systemic insulin resistance and eventually NASH." (PMID 34522493, 2021). "Macrophage-specific deletion of IRE1α reduced the high-fat diet-induced hepatic steatosis, insulin resistance, and also pro-inflammatory cytokines IL-1β or TNF." (PMID 32397116, 2020). "For instance, deacetylation of NLRP3 by SIRT2 reduces IL-1β production in macrophages, and hence improves aging-related inflammation and insulin resistance in rodents." (PMID 32545355, 2020). "Mechanistically, palmitic acid attenuates AMPK activation, which diminishes autophagy and induces mitochondrial ROS accumulation, leading to inflammasome activation as well as IL-1β-mediated insulin resistance." (PMID 32545355, 2020). "The transcription of inflammatory cytokines directly involved in the onset of insulin resistance (Il1β, Il6, and Tnfα) and chemotactic factors for macrophage recruitment (Mcp1) are restored to comparable levels in the cells never exposed to the pollutant." (PMID 33203037, 2020). "Studies shows that the key pro-inflammatory cytokines driving insulin resistance are TNFα and IL1β secreted by local macrophages." (PMID 32085416, 2020). "Specific to insulin resistance observed in T2DM is the involvement of the NLR family pyrin domain containing 3 (NLRP3) inflammasome, which activates inflammatory cytokines IL-1β and IL-18 and can lead to more severe insulin resistance." (PMID 33086602, 2020). "Meanwhile, increased pancreatic IL-1β, IL-6, and IL-8 decrease insulin gene expression in β-pancreatic cells, contributing to increased insulin resistance." (PMID 32903730, 2020). "Further, chronic IL-1β administration is able to induce insulin resistance in adipose tissue in vitro." (PMID 33178196, 2020).
Insulin resistance (continued). "MSC transplantation also reduces the levels of pro-inflammatory cytokines such as interleukin (IL)-6 and IL-1β, which are involved in the development of insulin resistance." (PMID 32010488, 2020). "Elevated IL-1β level triggers an inflammatory response, whereas suppressed adiponectin secretion triggers insulin resistance." (PMID 33379163, 2020). "In the present study, the administration of nicotinamide/streptozotocin resulted in an insulin resistance and an increase in the rate of IL-1β and TNF-α, confirming their involvement in the pathogenesis of type II diabetes." (PMID 33293987, 2020). "Systemically, the high serum concentrations of IL-6, IL-1β, and TNF-α increase insulin resistance and cause endothelial dysfunction, priming the vascular system to the development of diabetes-related diseases, including systemic arterial hypertension." (PMID 32903730, 2020). "Hyperglycemia is accompanied by an up-regulated expression of TNF-α, interleukin (IL)-1β, IL-6, and IL-18, which contribute to insulin resistance by both JNK and the IKKβ/NF-kβ pathway." (PMID 32431669, 2020). "Specifically, the proinflammatory cytokine TNF-α has been reported to induce insulin resistance, and previous studies have established the role of inflammatory cytokines IL-1β and IL-6 in the development and progression of T2DM." (PMID 32132984, 2020). "LPS is the activator of pro-inflammatory cytokines, such as TNF-α, IL-1β, and IL-6, contributing to the development of insulin resistance." (PMID 33329010, 2020). "After prolonged exposure to IL-1β in vitro, induced insulin resistance has been reported in murine and human adipocytes through a decrease in the expression of the glucose transporter Glut 4, which ultimately impairs insulin signaling and action." (PMID 33028018, 2020). "Considerable evidence points to a role for IL-1β in the development of insulin resistance and type 2 diabetes." (PMID 32221369, 2020). "The activation of NLRP3 inflammasomes to produce IL-1β leads to the coexistence of depressive-like behavior and insulin resistance in CUMS mice." (PMID 32166013, 2020). "Although IL-1β is a potent accelerator of chronic inflammation in adipose tissues that plays a central role in pathogenesis of insulin resistance, IL-1Ra exerts an anti-inflammatory effect by blocking the action of IL-1α and IL-1β on the IL-1 receptor." (PMID 31509948, 2019). "Cellular stresses are induced by the activation of thioredoxin-interacting protein and NLRP3 inflammasome, releasing increased amounts of IL-1β, contributing to β-cell dysfunction and insulin resistance." (PMID 30764536, 2019). "These phenomena are accompanied by abnormal release of FA, adipokines, and proinflammatory molecules including TNFα, interleukin (IL)-6, and IL-1β which, by acting on target organs, induce insulin resistance and favor the onset of type 2 diabetes." (PMID 31781039, 2019). "IL-1β is an important proinflammatory cytokine that drives the pathogenesis of liver inflammation, hepatic steatosis, liver fibrosis, and insulin resistance by impairing insulin signaling in the liver, muscle, and adipose tissue." (PMID 31485221, 2019). "As a result of this inflammation, the synthesis of pro-inflammatory cytokines (TNF-alpha, IL-6, and IL-1β) becomes increased and insulin resistance develops." (PMID 30881343, 2019). "Casp1 expresses Caspase 1, which governs the production of the pro-inflammatory cytokine IL1β, playing a role in the development of insulin resistance." (PMID 31614949, 2019). "IL-1α, IL-1β, and oxidative stress also induce insulin resistance by modulating IR or IRS-1 phosphorylation." (PMID 31581253, 2019). "Specifically, LPS-TLR activation of the NLRP3 inflammasome induces production of IL-1β resulting in insulin resistance, mitochondrial dysfunction, and ROS production, further NLRP3 activation and neuroinflammation and neurodegeneration." (PMID 31920905, 2019).
Insulin resistance (continued). "Remarkably, the low dose of EPR oil did not produce any significant effect on body weight but improved insulin resistance and reduced IL1β level beside amelioration of serum PRL, testosterone and gonadotropins." (PMID 32082253, 2019). "Collectively, these then produce greater amounts of pro-inflammatory cytokines, namely IL-1β, IL-6, and TNFα as well as chemokines such as MCP-1, which are causally associated with insulin resistance, dyslipidemia, and metabolic disease." (PMID 30736459, 2019). "Il1b-induced inflammation has been shown to be indirectly involved in insulin resistance in type 2 diabetes." (PMID 31316470, 2019). "It has been shown that increased concentrations of IL-1β and IL-6 contribute to the weakening of insulin signaling, presumably leading to insulin resistance." (PMID 31707362, 2019). "In so doing, GLP-1 prevents the cascade of events including IL-1β production culminating in insulin resistance, mitochondrial dysfunction and cellular stress." (PMID 31920905, 2019). "IL-1β promotes insulin resistance in tissues, thereby affecting distal vascular wall, skeletal muscle, myocardium, and kidney." (PMID 31073335, 2019). "Clinical evidence has documented an increase in caspase-1 activity and IL-1β secretion in adipose tissue macrophages from obese and T2D patients, and these patterns were tightly correlated with a condition of insulin resistance." (PMID 31200447, 2019). "M1 macrophages secrete the proinflammatory cytokines TNF-α, IL-1β, and IL-6, which promote insulin resistance and the accompanying deleterious metabolic effects, as well as synthesis of C-reactive protein." (PMID 31015797, 2019). "Endotoxemia (i.e., LPS in the blood) resulting from barrier dysfunction activates the NLRP3 inflammasome and results in mitochondrial dysfunction and IL-1b production and insulin resistance with important consequences for neuronal function." (PMID 31920905, 2019). "Activation of NLRP3 and subsequent IL-1β production are the single greatest factors that drive insulin resistance, and NLRP3 KO mice are protected from developing insulin resistance." (PMID 31920905, 2019). "Determining the effect of all SFs on adipocyte viability was a critical prerequisite to assess their capacity to control insulin resistance induced by dexamethasone and/or pro-inflammatory and pro-oxidant stress induced by IL-1β." (PMID 31527805, 2019). "The inflammatory milieu heightens the expression and release of proinflammatory cytokines, such as TNFα and IL-1β, which play a key role in damnification of insulin signaling, leading to insulin resistance and subsequently promoting NAFLD." (PMID 31215394, 2019). "It is well known that TNF-α promotes insulin resistance by inhibiting IRS1 (insulin receptor substrate 1) and IL-1β causes apoptosis in β-pancreatic cells, thereby diminishing insulin production." (PMID 31430882, 2019). "IL-1β is a predominant proinflammatory cytokine in insulin resistance of diabetics, and it is also a key cytokine in liver damage." (PMID 30937278, 2019). "Numerous researches have showed that the activation of NLRP3 inflammasome and the release of downstream IL-1β and IL-18 can promote the process of liver inflammation, triglyceride deposition, and insulin resistance during the NAFLD/NASH." (PMID 31827504, 2019). "In the intestinal immune system, the pro-inflammatory cytokine IL-1β plays an important role in insulin resistance and hyperlipidemia." (PMID 31551944, 2019). "In the other 31 cytokines, IL-1β (C7 and D7 spots in the array map) is regarded as a cytokine that activates multiple immune cells and promotes insulin resistance." (PMID 30687277, 2018). "The stimulation of NF-κB increased the levels of downstream inflammatory factors such as TNF-α, IL-1β, and IL-6, which promoted the insulin resistance in the liver." (PMID 30453687, 2018).